PIN1 (peptidylprolyl cis/trans isomerase, NIMA-interacting 1)
Description:
Peptidyl-prolyl cis/trans isomerase (PPIase) that binds to and isomerizes specific phosphorylated Ser/Thr-Pro (pSer/Thr-Pro) motifs. By inducing conformational changes in a subset of phosphorylated proteins, acts as a molecular switch in multiple cellular processes. Displays a preference for acidic residues located N-terminally to the proline bond to be isomerized. Regulates mitosis presumably by interacting with NIMA and attenuating its mitosis-promoting activity. Down-regulates kinase activity of BTK. Can transactivate multiple oncogenes and induce centrosome amplification, chromosome instability and cell transformation. Required for the efficient dephosphorylation and recycling of RAF1 after mitogen activation. Binds and targets PML and BCL6 for degradation in a phosphorylation-dependent manner. Acts as a regulator of JNK cascade by binding to phosphorylated FBXW7, disrupting FBXW7 dimerization and promoting FBXW7 autoubiquitination and degradation: degradation of FBXW7 leads to subsequent stabilization of JUN. May facilitate the ubiquitination and proteasomal degradation of RBBP8/CtIP through CUL3/KLHL15 E3 ubiquitin-protein ligase complex, hence favors DNA double-strand repair through error-prone non-homologous end joining (NHEJ) over error-free, RBBP8-mediated homologous recombination (HR). Upon IL33-induced lung inflammation, catalyzes cis-trans isomerization of phosphorylated IRAK3/IRAK-M, inducing IRAK3 stabilization, nuclear translocation and expression of pro-inflammatory genes in dendritic cells. Catalyzes cis-trans isomerization of phosphorylated phosphoglycerate kinase PGK1 under hypoxic conditions to promote its binding to the TOM complex and targeting to the mitochondrion. Acts as a negative regulator of adipocyte browning by binding to phosphorylated PRDM16, targeting PRDM16 for degradation (By similarity).
Synonyms: dod; UBL5
Tractability: Small molecule: a structure with a bound ligand is known; a high-quality ligand is known; it belongs to a druggable protein family. PROTAC: ubiquitination databases record sites on it; its protein half-life has been measured; a small molecule that binds it is known.
Target class: Isomerase; Enzyme
Chemical probes: BJP-06-005-3 (high quality), PIN1-3 (high quality)
Gene: Protein-coding gene on chromosome 19 (9,835,257 to 9,849,690, forward strand). Ensembl gene ENSG00000127445.
Subcellular location: Nucleus; Nucleus speckle; Cytoplasm
Subcellular location (Human Protein Atlas): Nucleoplasm; Cytosol
Pathways (Reactome):
Immune System: ISG15 antiviral mechanism; Negative regulators of DDX58/IFIH1 signaling
Signal Transduction: RHO GTPases Activate NADPH Oxidases
Gene Ontology:
Molecular function: beta-catenin binding; cis-trans isomerase activity; GTPase activating protein binding; mitogen-activated protein kinase kinase binding; peptidyl-prolyl cis-trans isomerase activity; phosphoserine residue binding; phosphothreonine residue binding; protein binding; ubiquitin ligase activator activity; cytoskeletal motor activity; phosphoprotein binding; tau protein binding
Biological process: cellular response to hypoxia; microtubule polymerization; negative regulation of amyloid-beta formation; negative regulation of cell motility; negative regulation of ERK1 and ERK2 cascade; negative regulation of protein catabolic process; negative regulation of SMAD protein signal transduction; negative regulation of transforming growth factor beta receptor signaling pathway; positive regulation of canonical Wnt signaling pathway; positive regulation of protein phosphorylation; positive regulation of transcription by RNA polymerase II; protein localization to mitochondrion; protein peptidyl-prolyl isomerization; protein stabilization; regulation of cytokinesis; regulation of gene expression; regulation of protein localization to nucleus; regulation of protein stability; response to hypoxia; Rho protein signal transduction; negative regulation of brown fat cell differentiation; neuron differentiation; protein destabilization; regulation of mitotic nuclear division; synapse organization
Cellular component: ciliary basal body; cytoplasm; cytosol; glutamatergic synapse; midbody; nuclear speck; nucleoplasm; nucleus; postsynaptic cytosol
Genetic constraint (gnomAD): Loss-of-function variants: 7 observed, 11.17 expected, observed/expected ratio (o/e) 0.63, 90% interval 0.35 to 1.18. The upper end of that interval is the gene's LOEUF score, 1.18, which puts it in group 5 of 6, group 1 being the genes least tolerant of losing a copy. Missense variants: 169 observed, 192.97 expected, observed/expected ratio (o/e) 0.88, 90% interval 0.77 to 1. Synonymous variants: 82 observed, 76.79 expected, observed/expected ratio (o/e) 1.07, 90% interval 0.89 to 1.28.
Homologues: Orthologues: chimpanzee PIN1 (100% identical), macaque PIN1 (100% identical), guinea pig PIN1 (98% identical), pig PIN1 (98% identical), mouse Pin1 (95% identical), mouse Pin1rt1 (90% identical), tropical clawed frog pin1 (80% identical), dog PIN1 (78% identical), zebrafish pin1 (69% identical), Caenorhabditis elegans pinn-1 (55% identical), Drosophila melanogaster CG32845 (39% identical). Paralogues in human: PIN4 (29% identical).
Diseases named in the same sentence as PIN1 in open-access papers:
PIN1 is named in the same sentence as 204 diseases in open-access papers, as found by Europe PMC text mining. Sharing a sentence is not in itself a finding about the gene and the disease. The quoted sentences say what the papers report.
breast carcinoma (108 papers, 2007 to 2026). "The types of cancers in which Pin1 is specifically implicated include prostate cancer, breast cancer, GBM, oral squamous cell carcinoma, NPC, gastric cancer, HCC, CCA, ICC, endometrial carcinoma, ESCC, acute myeloid leukemia, and pancreatic cancer." (PMID 39624096, 2024). "The rs2233678 polymorphism in the Pin1 promoter region (-842 G > C) has been shown to decrease the risk of cancers including breast cancer." (PMID 37508437, 2023). "In breast cancer, the increased levels of PIN1 have been linked to the acquisition of stem cell-like traits." (PMID 37370134, 2023). "Overall, these data provide new insights into the underlying molecular mechanism of IL-36γ in breast cancer and highlight the novel role of PIN1 in IL-36γ-induced tumorigenesis." (PMID 35954317, 2022). "In parallel, in G3 breast cancers, high Pin1 levels are associated with a worse clinical outcome in patients with high NDT signature." (PMID 24357640, 2014). "Pin1 inhibition impaired also self-renewal of CSCs derived from two aggressive primary breast cancers, demonstrating that loss of Pin1 activity impairs breast CSC self-renewal and replicative potential in a broad spectrum of breast cancer cells." (PMID 24357640, 2014). "In stratified analysis by cancer site, we found that −842G/C polymorphism in the PIN1 promoter region was statistically related with reduced breast cancer risks." (PMID 24013949, 2013). "Consistent with the critical regulatory role of PIN1 in cancer development, it has been reported that aberrant expression of PIN1 is associated with cancers, such as breast cancer and prostate cancer." (PMID 23976970, 2013). "The association of Pin1 with an aggressive biology in both prostate and breast cancers points toward a potential tumor-promoting function of Pin1." (PMID 19077306, 2008). "In PIN1, a gene previously reported to be mutated in breast cancer, we observed only one synonymous nucleotide change." (PMID 17224074, 2007). "Interestingly, rs2233678 and rs2233679 have also been shown to decrease Pin1 expression and are implicated in the decreased risk of breast cancer, lung cancer, and nasopharyngeal carcinoma." (PMID 32500074, 2020). "Pin1-deficient mice inhibit the massive proliferation of breast epithelium in pregnancy through reducing cyclin D1 levels and decreases β-catenin expression in breast cancer." (PMID 32258027, 2020). "The role of Pin1 in mediating ATO’s anticancer activity is further supported by the findings that human breast cancer cells were differentially susceptible to ATO and highly correlated with the rate of ATO-induced Pin1 degradation and with the expression of the ATO transporter AQP9." (PMID 30093655, 2018). "Of note, deregulated levels of Pin1 have been shown to disrupt cellular polarity of breast epithelial cells and found associated to high tumor grade and aggressiveness in breast cancer." (PMID 24357640, 2014). "Stem cell traits in a subpopulation of mammary tumor cells are thought to be implicated in treatment resistance and metastasis dissemination and high levels of Pin1 correlate with high grade breast cancer and chemoresistance." (PMID 24357640, 2014). "PIN1 polymorphisms and cancer risk was investigated in 7 kinds of cancer (hepatocellular carcinoma, laryngeal squamous cell carcinoma, squamous cell carcinoma of the head and neck, breast cancer, lung cancer, esophageal carcinoma and nasopharyngeal carcinoma)." (PMID 23976970, 2013).
breast carcinoma (continued). "PIN1 polymorphisms and cancer risk was investigated in 7 kinds of cancer (esophageal carcinoma, laryngeal squamous cell carcinoma, squamous cell carcinoma of the head and neck, hepatocellular carcinoma, breast cancer, lung cancer and nasopharyngeal carcinoma)." (PMID 23874525, 2013). "In contrast, PIN1 upregulation promotes oncogenesis in multiple cancers, including breast cancer and CRC, highlighting opposing pathological outcomes." (PMID 41241298, 2025). "This analysis revealedsignificant Pin1 overexpression in various cancers versus normal tissue,including breast cancer, pancreatic cancer, and HCC." (PMID 39051165, 2024). "This suggests a positive correlation between Pin1 levels and LC-3 expression, a representative indicator of autophagy, in estrogen receptor alpha-positive breast cancer." (PMID 38711994, 2024). "DAPK1 inhibits the ability of Pin1 to induce phagosome amplification and cell transformation in breast cancer." (PMID 39057063, 2024). "Pin1 also reduces myeloid cell leukaemia-1 (Mcl-1), which enhances chemo-resistance, and is thus positively correlated with poor survival in human breast cancer patients." (PMID 39624096, 2024). "Inhibition of Pin1 in breast cancer tissue suppresses NF-κB activation, suggesting Pin1 as a potential target for controlling aberrant NF-κB activation in cancer and related diseases." (PMID 39050887, 2024). "Accordingly, SENP1 has been shown to promote Pin1-dependent oncogenesis, and SENP1 and Pin1 expression levels are positively correlated in breast cancer tissue." (PMID 38745861, 2024). "The contribution of HIF- 2α towards metastasis in breast cancer can be further reinforced by the action of Peptidyl-prolyl cis-trans isomerase NIMA-interacting 1 (Pin1)." (PMID 39282472, 2024). "Background and Objectives: PIN1 is overexpressed in several human cancers, including prostate cancer, breast cancer, and oral squamous carcinomas." (PMID 39202474, 2024). "Astonishingly, Pin1 expression is elevated approximately 6-fold higher in CD24−/CD44+ breast cancer cells (CSCs) relative to non-CD24−/CD44+ breast cancer cells (non-stem cancer cells)." (PMID 38745861, 2024). "For instance, the deregulation of E2F during breast cancer promotes Pin1 expression, while the downregulation of the inhibitory phosphorylation of Pin1 leads to the accumulation of active Pin1." (PMID 38727267, 2024). "The current understanding of PIN1-YAP/TAZ pathway comes from studies performed in breast cancer, we firstly identified their relationship in OS." (PMID 37006999, 2023). "Presently, there are few studies on the mechanisms of action of TPL2 and Pin1 in the occurrence and development of breast cancer." (PMID 37833434, 2023). "YAP/TAZ are two major components of the Hippo pathway in breast cancer and are positively regulated by prolyl isomerase PIN1, we assessed their role in OS using both clinicopathological sections and western blots." (PMID 37006999, 2023). "Previous studies have reported that Pin1 promotes the oncogenic program of breast cancer through multiple mechanisms and is overexpressed in breast cancer cell lines and tissues." (PMID 37833434, 2023). "We observed a significant increase in PIN1 protein expression in breast cancer tissues (14 out of 20, 70%) compared to normal adjacent tissues." (PMID 37370134, 2023). "To further evaluate the effects of PIN1 on the IL-36γ-induced MAPK pathway in breast cancer, we overexpressed and knocked out PIN1 in MCF7 cells, followed by IL-36γ treatment." (PMID 35954317, 2022). "Binding to 15N-labeled Pin1 enzyme was performed using state-of-the-art 15N–1H HSQC NMR experiments to describe targeting breast cancer on a molecular level." (PMID 36014485, 2022).
breast carcinoma (continued). "Next, we found that both inhibition of PIN1 by juglone and KO of PIN1 potently reduced the tumorigenic potential of 4T1 metastatic mouse breast cancer cells and in vivo growth of breast tumors to some extent." (PMID 35954317, 2022). "We adopt the molecular hybridization technique to design new hybrids structurally containing benzimidazole core conjugated with different pharmacophores aiming to develop selective and more-effective anti-breast cancer agents via Pin1 inhibition." (PMID 36014485, 2022). "Pin1 can bind to estrogen receptor (ER), and it has a regulatory effect on the disordered AF1 of estrogen receptors alpha; also, it increases the DNA binding to (ER) so that the upregulation of Pin1 leads to different cancers, particularly breast cancer." (PMID 36014485, 2022). "The design, synthesis, and biological evaluation of new hybrids targeting Pin1 inhibition as anti-breast cancer agents were performed." (PMID 36014485, 2022). "Numerous researches indicated that Pin1 was a tumor-promoting gene in breast cancer by promoting proliferation, migration, metabolism of cancer cells." (PMID 34980129, 2022). "In the present study, we demonstrated that IL-34-induced MEK/ERK and JNK/c-Jun signaling is regulated by PIN1 in breast cancer." (PMID 33800170, 2021). "PIN1 is overexpressed in breast cancer and cooperates with RAS signaling to increase the transcriptional activity of c-Jun for tumorigenesis." (PMID 33800170, 2021). "In a previous report, the PIN1 inhibitor juglone has been shown to decrease the tumorigenicity of MCF7 breast cancer cells by inhibiting PIN1 activity." (PMID 33800170, 2021). "Inhibition of PIN1 prevents breast cancer development induced by oncogenes such as Neu or Ras in mice." (PMID 33800170, 2021). "Our study demonstrates the role of IL-34-induced MEK/ERK and JNK/c-Jun cascades in breast cancer and highlights the regulatory role of PIN1 in IL-34-induced breast tumorigenesis." (PMID 33800170, 2021). "In another breast cancer-related study, PIN1 was characterized as one of the major drivers of breast CSCs and their self-renewal and tumorigenicity." (PMID 32268506, 2020). "Pin1 induces the IL-22-induced proliferation and survival of breast cancer cells by activating c-Jun, and STAT3." (PMID 32258027, 2020). "The mRNA stability of PIN1 is reduced by microRNAs, such as miR-200c, miR-200b and miR296-5p in breast cancer, breast CSCs, and prostate cancer." (PMID 32258027, 2020). "A similar mechanism is also identified for Pin1-mediated stabilization of estrogen receptor a(ERa), a key player in the development of breast cancer." (PMID 32266261, 2020). "In breast cancer, the overexpression of PIN1 can regulate Notch signaling and increase cancer stem cell-like phenotypes, including tumorigenicity and drug resistance." (PMID 32300594, 2020). "PIN1 was shown to be overexpressed in tamoxifen-resistant breast cancer MCF-7 cells, which have undergone EMT, while PIN1-siRNA treatments downregulated the expression of mesenchymal markers and Snail." (PMID 32268506, 2020). "In breast cancer, high levels of both Akt-p-S473 and PIN1 predict a poorer prognosis than either alone." (PMID 32655497, 2020). "For example, miR-200c is reported to directly target the 3′-UTR of Pin1 mRNA, thus decreasing Pin1 level in breast cancer." (PMID 32296699, 2020). "All-trans retinoic acid (ATRA), a target drug used for acute promyelocytic leukemia (APL), binds to the substrate binding site of Pin1 and thus inhibits Pin1 activity in breast cancer." (PMID 31884567, 2020). "Inhibiting the phosphorylation of SMAD3 represses the aggressiveness of breast cancer by reducing the interaction with PIN1." (PMID 32258027, 2020). "Pin1 also interacts with Smad3 to drive oncogenic TGFβ signalling and promote breast cancer progression." (PMID 32347623, 2020).